TRIOBP (TRIO and F-actin binding protein)
Description:
[Isoform 1]: Regulates actin cytoskeletal organization, cell spreading and cell contraction by directly binding and stabilizing filamentous F-actin and prevents its depolymerization. May also serve as a linker protein to recruit proteins required for F-actin formation and turnover. Essential for correct mitotic progression. [Isoform 5]: Plays a pivotal role in the formation of stereocilia rootlets. [Isoform 4]: Plays a pivotal role in the formation of stereocilia rootlets.
Synonyms: KIAA1662; TARA; HRIHFB2122; TAP68; DFNB28; dJ37E16.4
Tractability: PROTAC: UniProt records ubiquitination sites on it; ubiquitination databases record sites on it; its protein half-life has been measured.
Gene: Protein-coding gene on chromosome 22 (37,697,048 to 37,776,556, forward strand). Ensembl gene ENSG00000100106.
Subcellular location: Nucleus; Nucleus (Isoform 1); Cytoplasm, cytoskeleton, microtubule organizing center, centrosome; Midbody; Chromosome, telomere
Pathways (Reactome):
Sensory Perception: Sensory processing of sound by inner hair cells of the cochlea; Sensory processing of sound by outer hair cells of the cochlea
Gene Ontology:
Molecular function: actin filament binding; ubiquitin protein ligase binding; myosin II binding; small GTPase binding
Biological process: positive regulation of substrate adhesion-dependent cell spreading; actin modification; barbed-end actin filament capping
Cellular component: actin cytoskeleton; focal adhesion; midbody; nucleus; centrosome; chromosome, telomeric region; stereocilium base
Genetic constraint (gnomAD): Loss-of-function variants: 169 observed, 221.97 expected, observed/expected ratio (o/e) 0.76, 90% interval 0.67 to 0.87. The upper end of that interval is the gene's LOEUF score, 0.87, which puts it in group 3 of 6, group 1 being the genes least tolerant of losing a copy. Missense variants: 2,835 observed, 3,028.2 expected, observed/expected ratio (o/e) 0.94, 90% interval 0.91 to 0.97. Synonymous variants: 1,149 observed, 1,230.8 expected, observed/expected ratio (o/e) 0.93, 90% interval 0.89 to 0.98.
Gene-disease validity (ClinGen):
ClinGen rates the evidence that TRIOBP causes each of these diseases.
hearing loss, autosomal recessive (autosomal recessive): Definitive.
Homologues: Orthologues: chimpanzee TRIOBP (89% identical), macaque TRIOBP (85% identical), rat Triobp (64% identical), mouse Triobp (63% identical), dog TRIOBP (24% identical), tropical clawed frog triobp (15% identical), zebrafish triobpa (13% identical), Drosophila melanogaster osp (10% identical), zebrafish triobpb (10% identical), Caenorhabditis elegans F10G8.8 (8% identical). Paralogues in human: MPRIP (17% identical).
Diseases named in the same sentence as TRIOBP in open-access papers:
TRIOBP is named in the same sentence as 30 diseases in open-access papers, as found by Europe PMC text mining. Sharing a sentence is not in itself a finding about the gene and the disease. The quoted sentences say what the papers report.
deafness (21 papers, 2012 to 2025). An inherited or acquired condition characterized by the complete loss of the ability to hear from one or both ears. "Concurrently, the functional implications of the TRIOBP c.2176C>T mutation and its role in causing deafness merit further investigation." (PMID 40336802, 2025). "In summary, this study first found a new suspected deafness pathogenic locus (c.A4484T and c.A4510G) in the TRIOBP gene in a family diagnosed with non-syndromic hearing loss, which provided new clues for the genetic variation of this family." (PMID 39533558, 2024). "Analysis of the previously reported TRIOBP variants in the literature as well as those from the current study implies that truncating variants involving exons 6 and 7 segregate with deafness and are therefore correctly classified as pathogenic mutations." (PMID 36029164, 2022). "DFNB28, a recessively inherited nonsyndromic form of deafness in humans, is caused by mutations in the TRIOBP gene (MIM #609761) on chromosome 22q13." (PMID 36029164, 2022). "DFNB28, a recessively inherited nonsyndromic form of deafness in humans, is caused by mutations in the gene TRIOBP (MIM #609761)." (PMID 36029164, 2022). "TRIOBP encodes a filamentous actin‐binding protein that has been identified as the gene for DFNB28 deafness." (PMID 32864763, 2020). "TRIOBP was the causal gene of autosomal recessive deafness (type 28), and 26 pathogenic variants in this gene have been identified in ClinVar." (PMID 32682410, 2020). "In the current study, we detected one reported and six novel mutations in 5 distinct deafness genes (TRIOBP, LHFPL5, CDH23, PCDH15, and MYO7A) in 5 recessive families." (PMID 29568747, 2018). "TRIOBP is a gene previously associated with deafness which encodes for several distinct protein species, each involved in actin cytoskeletal dynamics." (PMID 25333879, 2014). "The CG3217 protein shows homology to the human actin-bundling protein TRIOBP, which contributes to the rigidity of stereocilia in hair cells, and mutations in this gene cause deafness." (PMID 22530061, 2012). "The truncation of R2 repeat motifs in both alleles thus leads to a deafness phenotype by affecting the physiological role of TRIOBP by as yet unknown mechanisms." (PMID 36029164, 2022). "Mutations in TRIOBP could cause autosomal recessive deafness-28 (DFNB28), and surprisingly, several causal mutations were located within the human-specific insertion regions (e.g., R347X and Q297X)." (PMID 32337102, 2020). "While most TRIOBP mutations implicated in deafness were found in patients with severe or profound hearing loss detected before speaking, compound heterozygous mutations have been reported in patients with moderate hearing loss or later onset severe hearing loss." (PMID 33121024, 2020). "The TRIOBP c.1342C > T (p.Arg448*) variant is predicted to disrupt TRIOBP-5 and TRIOBP-4, which may lead to the congenital deafness." (PMID 32487028, 2020). "Finally, the fact that mutations in the TRIOBP locus are associated with deafness is interesting given that there exists data supporting a degree of comorbidity between hearing loss and psychiatric illness." (PMID 25333879, 2014). "Furthermore, the TRIOBP c.2176C>T mutation was also detected in the mother of the affected individual and additional relatives, aligning with the characteristics of autosomal recessive non-syndromic deafness." (PMID 40336802, 2025). "We identified two TRIOBP frameshift variants in this individual, heterozygous c.572delC p.Pro191Argfs*50, as well as a heterozygous insertion, c.3510_3513dupTGCA, p.Pro1172Cysfs*13 which demonstrated perfect segregation with the deafness phenotype on segregation analysis." (PMID 36029164, 2022). "Thus, the TRIOBP c.1342C > T (p.Arg448*) variant may also impair the DH-GEFs related pathwaws, contributing to the development of deafness in the individuals." (PMID 32487028, 2020).
deafness (continued). "The 15 associations included a missense lead variant in TMPRSS3, a known cause of Mendelian hearing loss, adding to the tally of Mendelian deafness genes (EYA4, CDH23, TRIOBP) showing common coding-variant associations with hearing loss in adult humans." (PMID 35661827, 2022). "Targeted NGS of 127 hearing loss‐related genes was carried out in the 9 probands, which allowed us to detect 5 reported and 5 novel variants in 6 distinct deafness genes including CDH23, GIPC3, MYO7A, TRIOBP, TECTA, and OTOF." (PMID 32864763, 2020). "Twelve homozygous mutations in known deafness genes, of which eight are novel, were identified in 12 families: MYO15A-p.Q1425X, -p.S1481P, -p.A1551D; LOXHD1-p.R1494X, -p.E955X; GIPC3-p.H170N; ILDR1-p.Q274X; MYO7A-p.G2163S; TECTA-p.Y1737C; TMC1-p.S530X; TMPRSS3-p.F13Lfs*10; TRIOBP-p.R785Sfs*50." (PMID 23226338, 2012). "Four recessive (TRIOBP, SLC26A4, GJB2, COL4A3) and one dominant (SOX10) for the deafness; six recessive genes (LRGUK, DNAH9, ARMC4, DNAH2, RSPH6A, and ACE) for male infertility can be conclusively ascribed." (PMID 38884051, 2024). "Our results also suggest that TRIOBP‐truncating variants in the C‐Terminal downstream of the repeat motifs R2 and of exon 7 are unlikely to interfere with the actin‐binding and bundling activities of the repeat motifs and are therefore unlikely to lead to a deafness phenotype." (PMID 36029164, 2022).
hearing loss (19 papers, 2014 to 2025). "Mutations in TRIOBP can cause autosomal recessive nonsyndromic deafness, which is associated with prelingual, severe to profound hearing loss." (PMID 40336802, 2025). "The aim of this study is to conduct a detailed analysis of the TRIOBP gene to uncover its specific role in non-syndromic hearing loss." (PMID 39533558, 2024). "By thoroughly studying the types, locations, and functional impact of TRIOBP gene mutations, we can gain a better understanding of its significance in the pathogenesis of hearing loss." (PMID 39533558, 2024). "In conclusion, this study will conduct an in-depth investigation into the genetic mechanisms and functional roles of the TRIOBP gene in non-syndromic hearing loss." (PMID 39533558, 2024). "Through these experiments, we aim to gain deeper insights into the specific regulatory mechanisms of the TRIOBP gene in the pathogenesis of hearing loss, providing a more scientific and accurate basis for diagnosis and treatment." (PMID 39533558, 2024). "Of the 16 hair cell-specific risk genes identified in our analysis, loss-of-function mutations in two are known to cause Mendelian hearing loss: TRIOBP and EYA4." (PMID 32986727, 2020). "While the majority of TRIOBP mutations found in patients with profound hearing loss lie within the reading frame of TRIOBP-4, these would also affect the TRIOBP-5 and 6 proteins." (PMID 33121024, 2020). "There have also been reported missense mutations within TRIOBP-1 in patients with hearing loss, however, these would also affect longer splice variants of TRIOBP." (PMID 33121024, 2020). "The first known gene, TRIOBP, to be associated with hearing loss has recently been linked to cancer." (PMID 29890989, 2018). "Considering their low frequency in ExAC and our Polish in-house WES databases, point variants in the TRIOBP gene seem to be a rare but important cause of non-syndromic hearing loss." (PMID 29197352, 2017). "A delayed onset of hearing impairment due to TRIOBP pathogenic variants creates a potential therapeutic window for future targeted therapies." (PMID 29197352, 2017). "Typically, TRIOBP pathogenic variants lead to prelingual, severe-to-profound hearing loss, thus the onset and degree of hearing impairment in our patients represent a distinct phenotypic manifestation caused by TRIOBP variants." (PMID 29197352, 2017). "The onset and degree of hearing impairment, characteristic for our patients, represent a unique phenotypic manifestation caused by TRIOBP pathogenic variants." (PMID 29197352, 2017). "Because of our TRIOBP results, we also looked at known Mendelian hearing loss genes, particularly the exons, and discovered two SNPs, which also had evidence of replication." (PMID 27764096, 2016). "Additionally, patients with moderate and/or progressive hearing loss have been described that possess both a mutation in TRIOBP-4 and a p.G1672* mutation on the other TRIOBP allele, which would affect only the longer splice variants." (PMID 33121024, 2020). "Positional candidate genes at these risk loci include TRIOBP, a gene associated with prelingual nonsyndromic hearing loss; ISG20, encoding a protein involved in interferon signaling; PCDH20, a member of the cadherin family; and SLC28A3, a nucleoside transporter." (PMID 32986727, 2020). "It is also noticeable that in one family from Pakistan in which three siblings displayed both schizophrenia and hearing impairment, along with epilepsy, homozygosity mapping implicated the causative mutation(s) to lie in one of two chromosomal regions, one of which includes the TRIOBP locus." (PMID 25333879, 2014). "Furthermore, additional techniques and methods, such as functional experiments, construction of cellular models, and expression analysis, will be employed to further validate the functional role of the TRIOBP gene and its association with non-syndromic hearing loss." (PMID 39533558, 2024).
hearing loss (continued). "Based on whole exome analysis, we identified two TRIOBP pathogenic variants (c.802_805delCAGG, p.Gln268Leufs*610 and c.5014G>T, p.Gly1672*, the first of which was novel) causative of nonsyndromic, peri- to postlingual, moderate-to-severe hearing loss in three siblings from a Polish family." (PMID 29197352, 2017). "TRIOBP, MYO6, and COL11A2 were found in both clinical gene sets (otoscope and clingen), and common variant studies of hearing loss (GWAS)." (PMID 38943082, 2024). "Mutations in hereditary deafness genes, such as TRIOBP, ILDR1, and EYA4, also exhibited significant correlations with age-related hearing impairment." (PMID 37062025, 2023). "TRIOBP (TRIO- and F-actin binding protein) is another gene that was replicated in our discovery cohort and is a well-established hearing loss gene, labelled as DFNB2849." (PMID 31645637, 2019). "In 2006, two research groups found that DFNB28 maps to chromosome 22q13.1 and is associated with TRIOBP-4 and TRIOBP-5 (TRIOBP-4/5) mutations in hearing loss patients in 15 families." (PMID 29890989, 2018). "TRIOBP is a binding protein for TRIO, a guanine nucleotide exchange factor and its mutations are associated with hearing impairment." (PMID 30140277, 2018). "These high priority genes, including MPHOSPH8, MYO18A, TRIOBP, OTOGL, TNC, and MYO6, were previously implicated in hearing loss, balance, and cochlear function, and were significantly enriched in common variant studies of hearing loss." (PMID 38943082, 2024). "Second, our findings point to multiple genes that have been reported to cause Mendelian forms of hearing loss previously, including EYA4, CDH23, TRIOBP, and GJB2, the latter being the most commonly reported gene in autosomal-recessive non-syndromic hearing loss." (PMID 35580588, 2022). "A key structural component of rootlets is TRIOBP (TRIO and F-actin binding protein), an actin-associated protein; highlighting its significance for the auditory system, mutations in TRIOBP cause hereditary hearing loss in humans." (PMID 31947734, 2020). "Although TRIOBP variants are not a frequent cause of hearing loss, this gene should be thoroughly analyzed also in patients with postlingual HI." (PMID 29197352, 2017). "Although TRIOBP alterations are not a frequent cause of hearing impairment, this gene should be thoroughly analyzed especially in patients with a postlingual hearing loss." (PMID 29197352, 2017). "While numerous mutations in TRIOBP have been associated with hearing loss, neither of these variants has been previously reported to be associated with hearing loss." (PMID 27764096, 2016). "Currently, the function of TRIOBP remains unclear, and no pathologies except hearing loss were caused by pathogenic variants in this gene." (PMID 32682410, 2020). "Motivated by our TRIOBP results, we also examined SNPs from our GWAS results in 132 known Mendelian hearing loss genes in GERA non-Hispanic whites at a reduced significance threshold adjusted for the proportion of the genome being tested to account for potential lack of power in these regions." (PMID 27764096, 2016). "ATE1 (Unigene0043244), TPRN (Unigene0030527), TRIOBP (Unigene0033824), GREB1 (Unigene0021168), and DPY19L2 (Unigene0017291) are thought to be related to nonsyndromic hearing impairment by damaging structures in the inner ear." (PMID 31528181, 2019).
schizophrenia (6 papers, 2014 to 2023). A major psychotic disorder characterized by abnormalities in the perception or expression of reality. "Among the proteins implicated as aggregating in schizophrenia is Trio and F-actin Binding Protein (TRIOBP)." (PMID 36232351, 2022). "Second, a polymorphism in the NDE1/miR-484 locus, previously associated with schizophrenia in the Finnish population, was found to affect the expression of TRIOBP transcripts." (PMID 33121024, 2020). "TRIOBP is the most significant DMR associated with recent marijuana use at Y20 and has been associated with general cognitive function, schizophrenia, and basophil count." (PMID 37258616, 2023). "First, in two screens of samples from separate brain banks, levels of TRIOBP transcripts were seen to be subtly, but significantly higher in schizophrenia patients than in the controls." (PMID 33121024, 2020). "In this study we further develop our epitope discovery paradigm, revealing TRIO binding protein (TRIOBP) to be the major substrate of a monoclonal antibody with high specificity to schizophrenia brain aggregomes." (PMID 25333879, 2014). "Each sample was therefore rated as either containing or not containing a distinguishable 72 kDa TRIOBP band, corresponding to full length TRIOBP-1 which is implicated as aggregating in schizophrenia." (PMID 36232351, 2022). "Of these, the TRIOBP-1 isoform, encoded at the 3′ end of the TRIOBP gene, was identified as seemingly being specifically insoluble in brain samples of schizophrenia patients as opposed to controls, using an antibody-based proteomics approach." (PMID 36232351, 2022).
glaucoma (2 papers, 2022 to 2026). Increased pressure in the eyeball due to obstruction of the outflow of aqueous humor. "Several genes, such as NMNAT2 and TRIOBP, had robust associations with both phenotypes, with potential IOP-independent therapeutic translation for glaucoma." (PMID 41674619, 2026).
skin cancer (2 papers, 2015 to 2020). "Overall, skin cancer had the highest somatic mutation frequencies for genes within cancer susceptibility regions, with SORCS3, CDKN2A, and TRIOBP all having mutations in over 10 % of samples." (PMID 26374197, 2015). "Furthermore, our analyses uncovered several recurring UV mutations following acute UVB radiation affecting multiple genes including HRNR, TRIOBP, KCNJ12, and KMT2C, which are frequently mutated in skin cancers, indicating their potential role as founding mutations in UV-induced skin tumorigenesis." (PMID 32188867, 2020).
glioblastoma (1 paper, 2022). The most malignant astrocytic tumor (WHO grade IV). "TRIOBP has been identified in a range of different cancers including lung carcinoma, glioblastoma, esophageal, pancreatic, prostate, lung, and breast cancer." (PMID 35906355, 2022).
hyperplastic polyp (1 paper, 2016). A polyp found mainly in the stomach and colon. "Finally, if also the patient (Co-657) with five hyperplastic polyps at an age of 73 years was considered a gene carrier, yet another three genes (SF3A1, GAL3ST1, TRIOBP) could be excluded." (PMID 26872740, 2016).